GDF15 (growth differentiation factor 15)
Diseases named in the same sentence as GDF15 in open-access papers (continued):
Sharing a sentence is not in itself a finding about the gene and the disease.
coronary atherosclerosis (7 papers, 2017 to 2024). Atherosclerosis of the coronary vasculature. "In patients with coronary atherosclerosis, GDF-15 levels have also been associated with chronic heart failure severity." (PMID 36093162, 2022). "We tested associations between GDF-15 and subclinical coronary atherosclerosis, assessed by coronary artery calcium (CAC) score, in COPD subjects free of clinical cardiovascular disease (CVD)." (PMID 28245821, 2017). "As a result, the level of serum GDF-15 in patients with coronary atherosclerosis was significantly higher than that in healthy people." (PMID 34539804, 2021). "We first compared the serum GDF-15 level between patients with coronary atherosclerosis and healthy people." (PMID 34539804, 2021). "Some previous reports have shown that elevated serum GDF-15 levels contribute to subclinical coronary atherosclerosis and are correlated with adverse outcomes such as exacerbation and lung function decline in COPD." (PMID 32847145, 2020). "In ever-smokers with COPD free of clinical CVD, GDF-15 contributes independently to subclinical coronary atherosclerosis." (PMID 28245821, 2017). "Furthermore, another study pointed that the increase in circulating GDF-15 levels predicted the severity of coronary atherosclerosis and CAD, as well as raised the mortality of adverse cardiovascular events." (PMID 35842724, 2022). "In controls, GDF-15 levels were found to be independently associated with LAPV, with each increase of 1 standard deviation (SD) associated with an increased odds ratio (OR) for coronary atherosclerosis of 35.08 (95% CI = 1.18->999, p = 0.04) after adjustment." (PMID 36093162, 2022).
hyperthyroidism (7 papers, 2018 to 2025). Overactivity of the thyroid gland resulting in overproduction of thyroid hormone and increased metabolic rate. "Secondly, logistic regression analysis confirmed an independent association between serum GDF15 levels and hyperthyroidism." (PMID 30687235, 2018). "In model 2, after adjustment for age, gender and BMI, serum GDF15 levels were also significantly associated with hyperthyroidism (OR [95% CI], 8.225 (4.805–15.380); P < 0.001)." (PMID 30687235, 2018). "In model 3, after further adjustment for ALT, AST, FBG and TC, Serum GDF15 levels remained independently associated with hyperthyroidism, with the adjusted OR (95% CI) of 13.193 (4.754–55.090; P < 0.001)." (PMID 30687235, 2018). "After adjustment for potential confounders, serum GDF15 levels were independently associated with hyperthyroidism." (PMID 30687235, 2018). "ORs for association between serum GDF15 levels and hyperthyroidism with the use of three logistic regression models." (PMID 30687235, 2018). "The results of current research suggest that hCG may be linked to temporary hyperthyroidism in impacted individuals and elevated GDF15 levels in HG-afflicted women." (PMID 40843754, 2025). "Therefore, our results provide the clinical and animal evidence that GDF15 is associated with hyperthyroidism." (PMID 30687235, 2018). "It would also be interesting to explore whether the neutralizing antibody against GDF15 could attenuate the hyperthyroidism-associated emaciation." (PMID 30687235, 2018). "Both experimental and clinical studies of hyperthyroidism have demonstrated that increased T4 levels lead to higher GDF-15 expression." (PMID 41302170, 2025). "Levels of GDF-15, which is considered a marker of biological age, were elevated in individuals with hyperthyroidism." (PMID 34627373, 2021). "Recent data suggest that another member of the TGF-β superfamily, GDF15, correlates with thyroid hormones being elevated in patients with hyperthyroidism, and that the treatment with thyroid hormone increases the expression of GDF15 in BAT in mice." (PMID 31248139, 2019). "Second, GDF15 was shown to suppress food intake, whereas hyperthyroidism is known to increase appetite." (PMID 30687235, 2018). "Firstly, we found that circulating GDF15 levels were markedly elevated in patients with hyperthyroidism compared with healthy subjects and dramatically declined after thionamide treatment." (PMID 30687235, 2018). "The authors also showed that treatment of hyperthyroidism reduced GDF15 values." (PMID 41303556, 2025). "However, even when thyroid hormone activates energy production, serum GDF-15 levels were elevated in patients with hyperthyroidism." (PMID 34627373, 2021). "In model 1, with no adjustment for any confounding factor, serum GDF15 levels were significantly associated with hyperthyroidism (OR [95% CI], 6.652 (4.184–11.353); P < 0.001)." (PMID 30687235, 2018). "Therefore, our results present the clinical relevance of GDF15 in humans under the condition of hyperthyroidism." (PMID 30687235, 2018). "Besides, we cannot rule out the possibility that other tissues not studied here might also contribute to the increased serum GDF15 during hyperthyroidism." (PMID 30687235, 2018).
hypertrophic cardiomyopathy (7 papers, 2012 to 2021). A condition in which the myocardium is hypertrophied without an obvious cause. "Stress conditions affect GDF-15 levels, and this, in turn, affects the regulation of myocyte hypertrophy and is therefore associated with the severity of hypertrophic cardiomyopathy." (PMID 33477548, 2021). "Although a study in hypertrophic cardiomyopathy reported an association of serum GDF-15 with AF diagnosis, this has not yet been assessed in aortic stenosis cohorts." (PMID 34441356, 2021). "There is evidence that serum growth differentiation factor 15 (GDF-15) is a clinically relevant inflammatory biomarker for several cardiovascular diseases, including hypertrophic cardiomyopathy." (PMID 33477548, 2021). "In community-based Individuals, postoperative patients and hypertrophic cardiomyopathy (HCM) patients, those who had the higher GDF-15 levels were more vulnerable to AF than the lower." (PMID 33115406, 2020).
multiple sclerosis (7 papers, 2019 to 2025). A progressive autoimmune disorder affecting the central nervous system resulting in demyelination. "A clinical trial reported elevated GDF15 levels in CSF of patients suffering from multiple sclerosis, especially in those with primary progressive multiple sclerosis." (PMID 40820083, 2025). "GDF15 has also been evaluated in patients with multiple sclerosis, where it represents a biomarker of a stable course of disease." (PMID 41303556, 2025). "While these observations can be explained by the induction of GDF-15 under inflammatory conditions, a completely different outcome is observed in multiple sclerosis." (PMID 32508832, 2020). "In a longitudinally sampled cohort of patients with multiple sclerosis, mean GDF-15 concentrations may serve as a biomarker for disease stability." (PMID 36935492, 2023). "Thus, in multiple sclerosis GDF-15 seems to be a biomarker for a stable course of disease rather than severity." (PMID 32508832, 2020). "GDF15 was measured in serum from patients with ME/CFS (n = 150; 100 with mild/moderate and 50 with severe symptoms), “healthy volunteers” (n = 150) and a cohort of patients with multiple sclerosis (n = 50)." (PMID 31801546, 2019). "To address this, we measured circulating levels of GDF15 in a clinically and biochemically phenotyped ME/CFS cohort, and compared them with distinct cohorts of healthy individuals and patients with multiple sclerosis (MS), all consenting participants from the UK ME/CFS Biobank (UKMEB)." (PMID 31801546, 2019).
pancreatic ductal adenocarcinoma (7 papers, 2016 to 2025). An infiltrating adenocarcinoma that arises from the epithelial cells of the pancreas. "Then, we performed several experiments, both in vitro and in vivo, to study the role and effects of GDF-15 in Pancreatic Ductal Adenocarcinoma." (PMID 33201838, 2020). "Taking together, we suggest that GDF-15 could be used as a biomarker of Pancreatic Ductal Adenocarcinoma." (PMID 33201838, 2020).
aortic stenosis (6 papers, 2018 to 2025). Aortic valve stenosis is a aortic valve disease caused by the incomplete opening of the aortic valve. "AF in severe aortic stenosis is associated with increased levels of pericardial fluid GDF-15." (PMID 34441356, 2021). "Moreover, a strong association of GDF-15 levels with the degree of aortic stenosis was found." (PMID 35455719, 2022). "The present manuscript describes similar quantifications in aortic stenosis patients with AF or SR patients when considering serum GDF-15 in the AVR setting." (PMID 34441356, 2021). "This study aimed to evaluate the association of GDF-15 and NT-pro-BNP in two different biological matrices (serum and pericardial fluid) with AF in severe aortic stenosis patients undergoing AVR, its association with atrial matrix remodeling, and 30-day postoperative outcomes." (PMID 34441356, 2021). "Key Findings: pericardial fluid GDF-15 and pericardial fluid and serum NT-pro-BNP were increased in AF patients with aortic stenosis." (PMID 34441356, 2021).
Brain atrophy (6 papers, 2015 to 2026). Partial or complete wasting (loss) of brain tissue that was once present. "Normalizing GDF15 function may result in the slowing of neuronal loss, possibly by protecting against stress-induced apoptosis, suggesting that GDF15 may be a potential therapeutic target to modulate the risk of brain atrophy." (PMID 38539657, 2024). "Since the causality between MIC-1/GDF15 and brain atrophy was uncertain, we also tested the possibility of Wave 1 GM volumes predicting changes in MIC-1/GDF15 serum levels over two years." (PMID 25867953, 2015).
head and neck cancer (6 papers, 2012 to 2025). A primary or metastatic malignant neoplasm affecting the head and neck. "Elevated GDF15 levels correlate with poor prognosis across several solid tumors, including colorectal, gastric, pancreatic, breast, lung, prostate, and head and neck cancers." (PMID 40868185, 2025). "Knockdown of GDF15 in breast, oral, and head and neck cancer cell lines sensitized resistant cells to IR." (PMID 38201456, 2023). "However, the function and mechanism of GDF15 in head and neck cancer (HNC) remains unclear." (PMID 34681812, 2021). "To explore whether GDF15 plays an oncogenic role in HNC, we evaluated GDF15 expression in normal and tumor tissues derived from the same head and neck cancer patients." (PMID 34681812, 2021).
Lewy body dementia (6 papers, 2016 to 2024). A progressive form of dementia characterized by the presence of protein deposits called Lewy bodies in the midbrain and cerebral cortex, and loss of cholinergic and dopaminergic neurons. "With respect to CSF measurements, GDF15 was increased in all Lewy body diseases, particularly for the PDD subgroup." (PMID 39737171, 2024). "Furthermore, serum GDF-15 levels in atypical parkinsonian syndromes other than PSP and MSA, such as corticobasal syndrome and Lewy body dementia, were not examined." (PMID 37755357, 2023).
liver cirrhosis (6 papers, 2015 to 2021). "As a result of chronic damage to hepatocytes, prolonged stimulation of hepatic stellate cells results in the release of profibrogenic abundant factors such as GDF-15, leading to the development of liver cirrhosis." (PMID 34777864, 2021). "GDF-15 is a cytokine involved in the process of fibrosis and the pathogenesis of numerous diseases including liver cirrhosis." (PMID 28430124, 2017). "In patients with liver cirrhosis, the serum selenium concentration was statistically lower, whereas serum IL-6 and GDF-15 concentrations were higher than those in the control group." (PMID 28430124, 2017). "Compared with HBV or HCV carriers, GDF15 had a sensitivity of 63.1% and a specificity of 86.6% at the optimal cut-off point of 2.463 ng/mL in patients with liver cirrhosis or HCC." (PMID 25996938, 2015). "Chronic and repetitive hepatocyte injury results in the overexpression of GDF15, and a dysregulation of GDF15 release may lead to prolonged stimulation of hepatic stellate cells (HSCs) and promote the progression of liver cirrhosis." (PMID 33178828, 2020).
migraine (6 papers, 2021 to 2025). "We found a genome-wide pleiotropy between higher levels of GDF15 and migraine risk." (PMID 35546551, 2022). "This trend continued in paediatric migraines as patients were found to have elevated GDF15 compared to controls." (PMID 40019842, 2025). "Serum GDF-15 and FGF-21 levels are increased in patients with migraine and associated with the severity of migraine-related disability." (PMID 36935492, 2023). "In the multiple regression that corrected for age, we found that the serum levels of FGF-21 and GDF-15 were significantly higher in migraine sufferers than in healthy controls." (PMID 36935492, 2023). "We calculated the area under the receiver operating characteristic (ROC) curve to evaluate the effectiveness of FGF-21 and GDF-15 prediction model for patients with migraine." (PMID 36935492, 2023). "The associations between the clinical variables of migraine patients and serum levels of FGF-21 and GDF-15 were studied." (PMID 36935492, 2023). "The heightened concentrations of GDF-15 and FGF-21 are linked to greater disease burden, indicating their potential as peripheral blood markers for evaluating the severity of migraine-related disability." (PMID 36935492, 2023). "Serum levels of both FGF-21 and GDF-15 in migraine patients were significantly higher than that in healthy controls (p < 0.001)." (PMID 36935492, 2023). "For the receiver operating characteristic (ROC) analysis, the diagnosis of migraine using GDF-15 showed that the area under the ROC curve (AUC) was 0.801 and the AUC of chronic migraine was 0.880." (PMID 36935492, 2023). "The higher concentrations of serum FGF-21 and GDF-15 observed in individuals with migraine and increased burden and disability suggest a potential correlation between disease severity." (PMID 36935492, 2023). "Regarding migraine-related disability, higher scores on the HIT-6 and MIDAS were associated with higher levels of FGF-21 and GDF-15." (PMID 36935492, 2023). "The area under curve (AUC) in predicting migraine, EM, CM in all subjects for GDF-15 was 0.801 (sensitivity 64.62%; specificity 89.66%), 0.780 (sensitivity 65.32%, specificity 86.29%), 0.880 (sensitivity 75.00%, specificity 92.00%), respectively." (PMID 36935492, 2023). "This study investigated the association between serum concentrations of the biomarkers FGF-21 and GDF-15, which have been investigated for mitochondrial diseases, and the presence of migraine." (PMID 34572118, 2021). "Elevated GDF-15 values were detected in the migraine group compared to the control group (506.65 ± 275.87 pg/mL vs. 403.34 ± 173.29 pg/mL, p < 0.001, Mann–Whitney U test)." (PMID 34572118, 2021). "In contrast, GDF-15 plasma levels were elevated in the migraine group (468.4 pg/mL, 348.3–606.1 pg/mL, n = 226) compared to controls (362.5 pg/mL, 287.0–493.3 pg/mL, n = 96, p < 0.001, Mann–Whitney U test)." (PMID 34572118, 2021). "It remains elusive for the role of FGF-21 and GDF-15 in migraine." (PMID 36935492, 2023). "The study found significantly heightened serum levels of FGF-21 and GDF-15 in patients with migraine compared to a control group, which suggests that both cytokines may have potential value in distinguishing between migraine sufferers and healthy controls." (PMID 36935492, 2023). "Hence, in this study, we analyzed serum concentrations of FGF-21 and GDF-15 in patients with migraine and healthy controls and the relationship of these cytokines with patients’ clinical parameters." (PMID 36935492, 2023). "The question of whether the levels of FGF-21 and GDF-15 can serve as a reference for the personalized use of nutraceuticals in the treatment of migraine is a topic that merits further investigation." (PMID 36935492, 2023). "Additionally, among the migraine group, higher concentrations of FGF-21 and GDF-15 were significantly correlated with increased migraine-related burden and disability, as evidenced by higher scores on the HIT-6 and MIDAS assessments." (PMID 36935492, 2023).
migraine (continued). "This study investigated whether the presence of migraine affects serum levels of FGF-21 and GDF-15, both of which have been implicated in metabolic disorders." (PMID 36935492, 2023). "The GDF-15 values of four participants of the control group and two patients from the migraine group were excluded from the statistical analysis as they could not be determined precisely due to technical problems." (PMID 34572118, 2021). "This study investigated whether serum concentrations of both FGF-21 and GDF-15 are altered in patients suffering migraine considering disease severity, attack morphology and concomitant disorders." (PMID 34572118, 2021). "Further studies, preferably in a younger group, could investigate the effect of vitamin B2 (riboflavin) and coenzyme Q 10 in migraine patients with elevated GDF-15 and/or FGF-21 levels." (PMID 34572118, 2021). "However, the results show an age-dependence of GDF-15 in migraine patients, and this should be considered in future studies." (PMID 34572118, 2021). "Migraine attacks were recently shown to be accompanied by elevated HIF-1α, FGF-21, GDF-15, CGRP, and PACAP-38 in medication-naïve children with migraine." (PMID 38369488, 2024). "The elevated levels of GDF-15 and FGF-21 in patients with migraine are insufficient to support the potential mechanism of mitochondria in migraine." (PMID 36935492, 2023). "Our research found a positive correlation between age and the concentrations of GDF-15 and FGF-21 not only in the migraine group but also in the healthy group." (PMID 36935492, 2023). "This study aimed to assess whether the presence of migraine affects serum levels of FGF-21 and GDF-15, and taking metabolic disorders into account as potential confounding factors." (PMID 36935492, 2023). "We have demonstrated that serum levels of GDF-15 and FGF-21 are elevated in patients with migraine." (PMID 36935492, 2023). "The study investigated whether the presence of migraine may influence FGF-21 and GDF-15 serum levels considering vascular and metabolic disorders as possible confounders." (PMID 34572118, 2021). "In a non-parametric analysis, elevated serum levels of GDF-15, but not FGF-21, were found in a large cohort of patients with migraine compared with an appropriately sized control group." (PMID 34572118, 2021).